GFAP (glial fibrillary acidic protein)
Diseases named in the same sentence as GFAP in open-access papers (continued):
Sharing a sentence is not in itself a finding about the gene and the disease.
retinal degeneration (continued). "All retinal degenerations tend toward a strong enrichment of the glial protein GFAP in Müller cells spanning the retina." (PMID 34439829, 2021). "To examine potential changes in the activation state of glial cells in the retina we performed immunostaining with the microglia marker Iba160 and GFAP, reported to accumulate in response to retinal degeneration." (PMID 32503050, 2020). "To study the characteristics of Müller cells in the rd1 mouse retina we carried immunostainings of GFAP at different stages of retinal degeneration in RP." (PMID 33424600, 2020). "Müller glia exhibited a dramatically increased expression of glial fibrillary-acidic protein (GFAP) during retinal degeneration." (PMID 33046772, 2020). "As Muller glial cell GFAP reactivity is a common indicator of glial hypertrophy and activation in retinal degeneration we compared GFAP immuno-staining between the control and Dicer CKO retina." (PMID 30783126, 2019). "NGF has been found to modulate retinal gliosis and decrease GFAP levels in different models of retinal degeneration or injury." (PMID 30006508, 2018). "The JAK-STAT pathway has been demonstrated to mediate the protection of photoreceptors in rd1 mice or light-induced retinal degeneration and be involved in the GFAP expression of Müller cells in the mouse model." (PMID 28404878, 2017). "Last, the expression of GFAP, characteristic of gliosis during retinal degeneration, was downregulated after MPEP delivery, which is consistent with a previous report in a COH rat model." (PMID 28615682, 2017). "In rd10 mice, Müller cells were also positive for GFAP (note the vertically oriented processes), indicating that they had become reactive during the retinal degeneration process (staining 3, green)." (PMID 24683495, 2014). "Our current study demonstrated that retinal degeneration accompanied by upregulation of TNFα and IL-6, GFAP and oxidative damage was ameliorated by blocking TNFα with Infliximab." (PMID 25301432, 2014). "Increased GFAP expression at early ages in CLN6nclf mice indicates reactive Müller cell gliosis as a prominent early event in retinal degeneration." (PMID 24124525, 2013). "The marker for glial cell activation, GFAP, is often significantly upregulated in inherited retinal degeneration mouse models and induced retinal injuries." (PMID 23687432, 2013). "The elevated expression of GFAP by Müller cells reflects the induction of gliotic responses characteristic of retinal degeneration." (PMID 17786210, 2007). "However, in RD retinas, 60% of Müller glia were GFAP+, reflecting their activation and gliotic response to retinal degeneration (Sarthy, Dudley, and Haldin 2018)." (PMID 39873321, 2025). "However, staining for glial fibrillary acidic protein (GFAP) to identify activated Müller glia, suggested reactive gliosis in the three experimental groups, supporting the notion of retinal degeneration." (PMID 39463155, 2024). "GFAP is commonly upregulated in retinal degeneration models, where the reduction in GFAP may indicate reduced gliosis." (PMID 37443724, 2023). "It is thought that increased GFAP expression in inherited retinal degeneration and AMD may reflect the secondary response to a primary insult to another cell type." (PMID 35955937, 2022). "However, previous works have shown that there is a relationship between GFAP immunohistochemistry and GFAP expression in other animal models of retinal degeneration." (PMID 33008136, 2020). "Additionally, in P23H rat retinas, GFAP expression also increases with the age of the animal, indicating enhanced activation of glial cells in the advanced stages of retinal degeneration." (PMID 26733810, 2015). "Previous studies have shown that during retinal degeneration, the Müller cells present a marked modification in protein expression, beginning to express filament protein such as GFAP and also vimentin that may change the structure density of the cells." (PMID 21901134, 2011).
retinal degeneration (continued). "Moreover, it has been reported that in rats, increases in GFAP within the SC follow 3, 3′-iminodipropionitrile-induced retinal degeneration, which is known to disrupt neurofilaments and axonal transport." (PMID 19347051, 2009). "In order to investigate if the data from the mouse model correspond to the characteristics of retinal degeneration in patients, three human retina samples containing drusen and three samples without drusen were stained with the selected gliotic markers (vimentin, nestin, GFAP, and S100β)." (PMID 37298126, 2023). "Nevertheless, CRALBP and GFAP, which are markers of amacrine cells and Müller glial cells respectively, were highly upregulated suggesting that they might be involved in the exacerbation of retinal degeneration during RP." (PMID 28258056, 2017). "Indeed at a late stage of Rho-/- retina degeneration, an increased GFAP expression was observed with many processes surrounding the remaining photoreceptors suggesting a transformation of the OLM probably by reinforcing the barrier effect of the Müller cells endfeet." (PMID 21901134, 2011). "RPGR-ROs exhibited increased expression of glial fibrillary acidic protein (GFAP), indicative of reactive gliosis, a phenomenon commonly observed in various forms of retinal degeneration." (PMID 39422807, 2025). "Upregulation of glial fibrillary acidic protein (GFAP) is a well-established marker for cellular stress and gliosis often occurs before or concurrent with retinal degeneration in other mouse models of retinal diseases and in Ush2a−/− mice." (PMID 36810733, 2023). "Protein expression analysis also showed significantly greater GFAP levels in P360 vs. P120 P23H rat retinas (ANOVA, Bonferroni's test, P < 0.01), indicating that GFAP expression increased in P23H rats during retinal degeneration." (PMID 26733810, 2015). "In male mice, GFAP levels were elevated at P8 in the ganglion cell layer (GCL), as well as the outer and inner nuclear layers (ONL and INL) of the retina, and remained high through P10, reflecting a sustained gliotic response to retinal degeneration." (PMID 40358187, 2025). "Müller cells showed no elevated labeling for GFAP, a sensitive marker of reactive gliosis and retinal degeneration." (PMID 32780351, 2020). "Glial fibrillary acidic protein (GFAP), a marker of retinal gliosis which is upregulated upon MP activation and used as an index of retinal degeneration, was dramatically increased throughout most of the entire retina; this effect was largely prevented by rytvela and Kineret." (PMID 33246504, 2020). "After 1 day of continuous exposure (15,000 Lux), BALB/c neural retinas showed no obvious signs of retinal degeneration, but increased expression of GFAP." (PMID 32242818, 2020).
encephalitis (59 papers, 2010 to 2026). An acute inflammatory process affecting the brain parenchyma. "Our case–control study revealed an increase in plasma GFAP levels in patients with severe EV-A71 infection, suggesting that the activation of astrocytes is associated with the occurrence of EV-A71 encephalitis." (PMID 39679722, 2025). "While acyclovir effectively treats encephalitis caused by these viruses, its efficacy is suboptimal when GFAP is involved with EBV." (PMID 38585352, 2024). "Here, we report a case of GFAP astrocytopathy caused by VE, which presented as bimodal encephalitis and was refractory to glucocorticoid therapy." (PMID 37781407, 2023). "Although GFAP-associated encephalitis has been reported in the literature, evidence related to the clinical course, recurrence, and outcomes of the disease remains lacking." (PMID 37079256, 2023). "After fatal cases of drug reaction with eosinophilia and systemic symptoms and severe inflammatory brain disorders, e.g. anti-NMDA-encephalitis and anti-GFAP-IgG associated encephalitis, daclizumab was finally withdrawn from the market." (PMID 33324871, 2019). "Finally, we provided insight into an early phase of GFAP autoimmunity in an autopsy of a pug dog encephalitis that was characterized by marked meningoencephalitis with selective astrocytic damage with loss of GFAP and AQP4 in the lesions." (PMID 38310187, 2024). "A severe axonal sensorimotor neuropathy associated with GFAP-Abs encephalitis and Epstein–Barr virus (EBV) DNA in the CSF has been reported, which the authors hypothesized to be a possible trigger for the autoimmune response." (PMID 37540278, 2023). "Anti-NMDAR encephalitis combined with GFAP-IgG is uncommon, and repeated tests for AE-associated antibodies may be required in patients with recurrent encephalitis." (PMID 36253739, 2022). "Glial fibrillary acidic protein (GFAP) antibody may be found in these cases of meningitis but are often associated with encephalitis, myelitis or optic disk edema." (PMID 33897597, 2021). "Hearing loss has been reported in other types of autoimmune encephalitis as well, such as in Kelch-like protein-11, NMDA, LGI1, GABAA, and GFAP encephalitis." (PMID 41598359, 2026). "Further workup revealed anti-N-methyl-D-aspartate receptor (anti-NMDAR) encephalitis and autoimmune glial fibrillary acidic protein (GFAP) astrocytopathy as the etiology." (PMID 41422202, 2025). "To underscore the clinical significance of our findings, we determined the plasma GFAP concentration in both patients with mild EV-A71 infection and patients with severe EV-A71 infection (who had encephalitis) EV-A71." (PMID 39679722, 2025). "Briefly, the encephalitis groups exhibited increased GFAP, sTREM2, YKL-40, and IL-1β compared to controls, with similar findings in the Cov-Enceph and Enceph groups." (PMID 40036349, 2025). "GFAP-A is positive for anti-GFAP antibodies, accompanied by linear enhancement around the ventricles and symptoms of meningeal/encephalitis/myelitis, often accompanied by tumors." (PMID 40678340, 2025). "(Note: Anti-IgLON5 and anti-GFAP encephalitis cases were excluded from tabular presentation due to limited sample size [n = 2 each])." (PMID 40170898, 2025). "On the basis of the patient’s symptoms and signs, GFAP encephalitis was diagnosed and treated with methylprednisolone and immunoglobulin." (PMID 38996095, 2024). "An acute evolution in a pug dog encephalitis allowed us to provide insight into an early phase of GFAP autoimmunity in a canine autopsy case." (PMID 38310187, 2024). "In a subject with proven anti-GABAAR receptor encephalitis, biopsy of the right frontal cortex revealed increased expression of glial fibrillary acidic protein (GFAP) signifying astroglial activation and gliosis." (PMID 38146643, 2024). "In contrast, seizures occur in only 27.6% of cases of anti-glial fibrillary acidic protein [GFAP] (95% CI 12.7–47.2%) encephalitis." (PMID 37034075, 2023).
encephalitis (continued). "GFAP encephalitis is sensitive to hormones, but the effect of human immunoglobulin on GFAP encephalitis is unclear and needs to be further studied in depth." (PMID 36647033, 2023). "GFAP shares most of the prevalent features of encephalitis with its certain specificities, e.g., tremor bowel and urinary." (PMID 37079256, 2023). "One patient had viral encephalitis one month prior, and the other had staphylococcal meningitis 2 weeks before the GFAP-IgG was discovered." (PMID 37205100, 2023). "Herein, we describe a case of anti-NMDAR encephalitis with overlapping symptoms of GFAP antibody positivity." (PMID 36371153, 2022). "CSF GFAP-IgG and CSF NMDAR-IgG can also cause autoimmune encephalomyelitis or encephalitis, respectively, rendering it impossible to attribute these patients’ clinical and paraclinical features to either of these antibodies with sufficient certainty." (PMID 35907972, 2022). "A diagnosis of anti-GFAP encephalitis was made, although the prominent clinical features were of anti-NMDAR encephalitis." (PMID 36371153, 2022). "Many forms of autoimmune meningitis such as GFAP encephalitis, and AQP4 encephalitis can mimic the features of intracranial infection such as TBM, but are naturally unresponsive to antibiotic or antiviral treatment." (PMID 36362480, 2022). "Patients with unusual symptoms of anti-NMDAR encephalitis should also be tested for anti-GFAP antibodies." (PMID 36371153, 2022). "Twenty-eight were of anti-NMDA-receptor encephalitis with other cases associated with antibodies against LGi1, Caspr2, glycine receptor, DPPX, GABAB receptor, IgLON5, GFAP, and SOX1." (PMID 33692738, 2021). "Glial fibrillary acidic protein (GFAP) autoimmune astrocytopathy is characterized by GFAP autoantibody positive encephalitis, meningoencephalitis or meningoencephalomyelitis." (PMID 33297961, 2020). "Astrocytes and their autoimmune glial fibrillary acidic protein (GFAP) have also been shown to be associated with AE including NMDAR encephalitis and other encephalitis mimicking LE, and play important roles in neuroinflammation." (PMID 33396564, 2020). "In one of the VA1-associated encephalitis cases, VA1 capsid was localized to astrocytes by immunohistochemistry performed with costaining for GFAP." (PMID 31289185, 2019). "Similar effects have been observed in cultured NSCs/NPCs treated with Tat or direct HIV-1 infection, as well as in mice with HIV-1 encephalitis, doxycycline-inducible GFAP-Tat transgenic mice, and GFAP-gp120 mice." (PMID 30314515, 2018). "The main clinical phenotypes in the GFAP‐astrocytopathy group included meningoencephalitis (48%), meningoencephalomyelitis (35%), isolated encephalitis (10%), and isolated myelitis (7%), with one case of non‐longitudinally transverse myelitis affecting the cervical cord." (PMID 40581835, 2025). "Therefore, immune-related encephalitis, including autoimmune encephalitis and GFAP encephalitis, was considered, and further testing for autoimmune encephalopathy-related antibodies revealed GFAP antibodies in the cerebrospinal fluid." (PMID 38996095, 2024). "A high clinical awareness of GFAP-A is therefore necessary in the diagnostic workup of patients with noninfectious encephalitis and meningeal features, and prompt testing of GFAP-IgG is recommended." (PMID 39975853, 2024). "A recent study identified elevated glial fibrillary acidic protein (GFAP) in patient serum from acute VEEV and Madariaga virus (MADV) infections; however this biomarker was not specific to alphavirus infection as bacterial cases with encephalitis also displayed elevated GFAP." (PMID 39734493, 2024). "Then, GFAP-Abs testing was performed in patients recruited by the two French reference centers for CNS inflammatory diseases who were mainly patients presenting with signs of encephalitis or myelitis." (PMID 37540278, 2023).
encephalitis (continued). "According to our data, we recommend maintaining vigilance against cases of suspected viral encephalitis with poor response to antiviral therapy, and the detection of GFAP‐IgG and EBV may facilitate the early diagnosis in these patients." (PMID 37458208, 2023). "Anti-LGI1 encephalitis patients have elevated neurofilament light chain protein, glial fibrillary acidic protein and chemokine ligand 13 levels and reduced Visinin-like protein 1, Synaptosomal Associated Protein-25 (SNAP-25) and neurogranin levels in the serumand CSF." (PMID 36685530, 2022). "For example, anti-NMDAR encephalitis may co-exist with a demyelinating disease in the presence of anti-MOG or anti-GFAP antibodies." (PMID 36211351, 2022). "A GFAP-antibody positive meningo-encephalitis is a steroid-responsive encephalitis that may be accompanied with meningitis, myelitis, and optic disc edema and evidence of inflammation in CSF." (PMID 35903170, 2022). "The cases of anti-IgLON5 encephalitis and anti-GFAP encephalitis both required ICU admission." (PMID 33692738, 2021). "Anti-GFAP astrocytopathy should be included in the differential diagnosis of patients who present with subacute meningitis with negative microbiological studies and a progressive clinical course including encephalitis and/or myelitis." (PMID 33297961, 2020). "In addition longitudinally extensive myelitis lesions were recently described in patients with symptoms of meningitis, encephalitis and/or myelitis that were tested positive for glial fibrillary acidic protein (GFAP)-IgG." (PMID 30405519, 2018). "Apraxia, as seen in our patient, has been described in GFAP astrocytopathy and in anti-NMDAR encephalitis; however, it appears to be an infrequent manifestation compared with other cognitive and behavioral changes." (PMID 41422202, 2025). "Two of these patients were diagnosed with anti‐NMDAR encephalitis, one had anti‐MOG Ab, and the other had anti‐GFAP Ab." (PMID 40583162, 2025). "The clinical phenotypes in the GFAP-MOG group included meningoencephalomyelitis (n = 2), encephalomyelitis (n = 2), meningoencephalitis (n = 2), and encephalitis (n = 1); notably, five patients with ON." (PMID 40777035, 2025). "The diagnosis was adjusted to GFAP astrocytopathy with anti-NMDAR and sulfatide-IgG-positive encephalitis overlap syndrome." (PMID 38996095, 2024). "A new entity characterized by anti-glial fibrillary acidic protein (GFAP) antibodies has been recently identified in patients manifested with inflammatory CNS symptoms such as meningitis, encephalitis, and myelitis." (PMID 38137014, 2023). "Previous studies reported no significant changes in the overall number of GFAP‐positive astrocytes in the hippocampus of anti‐NMDAR encephalitis mice." (PMID 41489316, 2026). "At that time, GFAP-IgG was negative, and the clinical picture was initially considered consistent with viral encephalitis." (PMID 41181139, 2025). "In this case report, we present a case of bimodal encephalitis, which includes VE and Autoimmune GFAP astrocytopathy, with no precise interval between the two, posing a diagnostic challenge." (PMID 37781407, 2023). "Additionally, similar radiological patterns have been reported in cases of encephalitis with negative anti-GFAP antibodies." (PMID 39267735, 2024). "Therefore, we recommend testing for GFAP antibodies in patients with viral encephalitis who do not respond to antiviral therapy and checking for CSF infection status in patients with anti-GFAP antibodies." (PMID 37205100, 2023). "Another patient with a chronic recurrent course had manifestations of encephalitis in the early stage with significant psychiatric symptoms and multiple intracranial lesions with gadolinium enhancement and was NMDAR-IgG-positive but GFAP-IgG-negative in the CSF." (PMID 36552122, 2022).
encephalitis (continued). "Combined ISH with GFAP staining was performed on sections from 4 cases of SIVE, 3 cases of SIV without encephalitis, AD and schizophrenia, 2 cases of Pick's disease and infarct and one case of MS and ALS." (PMID 20540736, 2010).